OR4D9 (olfactory receptor family 4 subfamily D member 9)
Description:
Odorant receptor.
Synonyms: OR11-253
Tractability: Small molecule: it belongs to a druggable protein family. Antibody: UniProt places it where antibodies can reach, with medium confidence; UniProt predicts a signal peptide or a membrane-spanning region; its Gene Ontology location is reachable by antibodies, with medium confidence.
Gene: Protein-coding gene on chromosome 11 (59,511,368 to 59,520,703, forward strand). Ensembl gene ENSG00000172742.
Subcellular location: Cell membrane
Pathways (Reactome):
Sensory Perception: Expression and translocation of olfactory receptors
Gene Ontology:
Molecular function: olfactory receptor activity; G protein-coupled receptor activity
Biological process: detection of chemical stimulus involved in sensory perception of smell; G protein-coupled receptor signaling pathway
Cellular component: plasma membrane; membrane
Genetic constraint (gnomAD): Loss-of-function variants: 3 observed, 1.7 expected, observed/expected ratio (o/e) 1.76, 90% interval 0.62 to 1.94. That is too few expected variants to judge how well the gene tolerates losing a copy. Missense variants: 393 observed, 393.87 expected, observed/expected ratio (o/e) 1, 90% interval 0.92 to 1.09. Synonymous variants: 145 observed, 155.86 expected, observed/expected ratio (o/e) 0.93, 90% interval 0.81 to 1.07.
Homologues: Orthologues: chimpanzee OR4D9 (98% identical), macaque OR4D9 (94% identical), rabbit OR4D9 (89% identical), dog OR4D9 (87% identical). Paralogues in human: OR4D11 (81% identical), OR4D10 (78% identical), OR4D6 (67% identical), OR4D2 (63% identical), OR4D1 (62% identical), OR4D5 (61% identical), OR4N5 (49% identical), OR4L1 (49% identical), OR4N2 (48% identical), OR4A15 (48% identical), OR4E2 (48% identical), OR4K14 (48% identical), and 116 more.